PLK5 (polo like kinase 5 (inactive))
Description:
Inactive serine/threonine-protein kinase that plays a role in cell cycle progression and neuronal differentiation.
Synonyms: PLK-5; PLK5P; SgK384ps
Tractability: No criterion of Open Targets' tractability assessment is met for any kind of drug.
Gene: Protein-coding gene on chromosome 19 (1,508,023 to 1,536,046, forward strand). Ensembl gene ENSG00000185988.
Subcellular location: Nucleus, nucleolus; Cytoplasm
Gene Ontology:
Molecular function: ATP binding; protein kinase activity
Biological process: cellular response to growth factor stimulus; defense response to tumor cell; positive regulation of neuron projection development; regulation of apoptotic process; regulation of G1/S transition of mitotic cell cycle; DNA damage response; mitotic spindle organization; regulation of cell cycle process
Cellular component: cytoplasm; centrosome; kinetochore; nucleus; spindle pole; nucleolus
Genetic constraint (gnomAD): Loss-of-function variants: 29 observed, 30.79 expected, observed/expected ratio (o/e) 0.94, 90% interval 0.7 to 1.28. The upper end of that interval is the gene's LOEUF score, 1.28, which puts it in group 5 of 6, group 1 being the genes least tolerant of losing a copy. Missense variants: 491 observed, 447.15 expected, observed/expected ratio (o/e) 1.1, 90% interval 1.02 to 1.18. Synonymous variants: 225 observed, 198.56 expected, observed/expected ratio (o/e) 1.13, 90% interval 1.02 to 1.27.
Homologues: Orthologues: chimpanzee PLK5 (95% identical), dog PLK5 (71% identical), macaque PLK5 (70% identical), mouse Plk5 (66% identical), rat Plk5 (64% identical), tropical clawed frog plk5 (35% identical). Paralogues in human: PLK3 (37% identical), PLK2 (33% identical), PLK1 (27% identical), PLK4 (24% identical).
Diseases named in the same sentence as PLK5 in open-access papers:
PLK5 is named in the same sentence as 23 diseases in open-access papers, as found by Europe PMC text mining. Sharing a sentence is not in itself a finding about the gene and the disease. The quoted sentences say what the papers report.
brain tumor (3 papers, 2012 to 2022). "Thus, PLK5 is a kinase-deficient polo box domain-containing protein with exclusive neurological function and brain tumor suppressor activity." (PMID 35256538, 2022). "Unlike other Plks (Plk1,2,3 and 4), the function of Plk5 in cancer development is not yet well understood, but it was recently shown to localize in the nucleus in response to DNA damage and was silenced in brain tumor tissues." (PMID 26908440, 2016).
breast carcinoma (2 papers, 2022 to 2024). "Specifically, in breast cancer, emerging biomarkers such as polo-like kinase (PLK) PLK 2, PLK3, and PLK5 have been validated as significant prognostic indicators through survival analysis utilizing the Kaplan–Meier Plotter database." (PMID 39432619, 2024). "Six of these genes (MUM1, AC016876.1, PLK5, HCN2, OAZ1, AC027307.2) have been identified as prognostic features for many cancers, such as colorectal cancer, breast cancer, non-small cell lung cancer." (PMID 36304471, 2022).
glioblastoma (2 papers, 2022 to 2025). The most malignant astrocytic tumor (WHO grade IV). "The PLK5 gene has been reported to be altered in glioblastoma and, along with other members of the PLK family, plays a role in cell division and centriole duplication." (PMID 40981433, 2025). "PLK5 is frequently silenced in astrocytoma and glioblastoma due to hypermethylation." (PMID 35256538, 2022).
lymph node metastasis (2 papers, 2016 to 2022). "Additionally, decreased PLK5 protein was linked with increased pathological grade (P = 0.002), lymph node metastasis presence (P = 0.001), elevated tumor-node-metastasis (TNM) stage (P = 0.003), and abnormal cancer antigen 125 (CA125) (P = 0.002)." (PMID 36684318, 2022).
non-small cell lung carcinoma (2 papers, 2022). A group of at least three distinct histological types of lung cancer, including non-small cell squamous cell carcinoma, adenocarcinoma, and large cell carcinoma. "A review argues that polo-like kinase 5 (PLK5) may be linked to unfavorable prognosis in non-small cell lung cancer (NSCLC) patients, which contradicts the discoveries from The Human Protein Atlas database (derived from TCGA analysis)." (PMID 36684318, 2022).
Alzheimer disease (1 paper, 2023). A progressive, neurodegenerative disease characterized by loss of function and death of nerve cells in several areas of the brain leading to loss of cognitive function such as memory and language. "PLK5 is a crucial gene involved in learning and memory expressed mainly in the hippocampus; this gene’s function is altered in Alzheimer’s disease." (PMID 37761940, 2023).
diabetes (1 paper, 2022). "Nevertheless, no linkage was found between tumor PLK5 mRNA expression and other disease features, including age, gender, smoking, drinking, hypertension, hyperlipidemia, diabetes, subtype, tumor size, LYN metastasis, ECOG PS score, and CEA, in NSCLC patients (all P > 0.05)." (PMID 36684318, 2022).
glioma (1 paper, 2022). A benign or malignant brain and spinal cord tumor that arises from glial cells (astrocytes, oligodendrocytes, ependymal cells). "However, the expression levels of PLK5 decreased as the WHO grades of glioma increased." (PMID 35256538, 2022).
Huntington disease (1 paper, 2023). Huntington disease (HD) is a rare neurodegenerative disorder of the central nervous system characterized by unwanted choreatic movements, behavioral and psychiatric disturbances and dementia. "These genes, RET and PLK5, play a significant role in movement-related functions, but their expression is downregulated in Huntington’s disease (HD)." (PMID 37761940, 2023).
lung adenocarcinoma (1 paper, 2021). A carcinoma that arises from the lung and is characterized by the presence of malignant glandular epithelial cells. "While compared to normal sample, PLK5 showed no differential expression either in lung adenocarcinoma or in lung squamous cell carcinoma." (PMID 34080290, 2021).
lung carcinoma (1 paper, 2017). "However, we also identified other genes that may represent novel epigenetically inactivated lung cancer-related target genes (e.g. pyrimidinergic receptor P2RY﻿6 and PLK5)." (PMID 28634396, 2017).
onchocerciasis (1 paper, 2023). Onchocerciasis is a form of filariasis, caused by the parasitic worm Onchocerca volvulus, transmitted by the black fly. "Additional strong candidates included OVOC1523/ATP synthase, OVOC247/laminin and OVOC11626/PLK5, and along with OVOC11613, and were also detected in urine samples from onchocerciasis patients." (PMID 36435333, 2023).
ovarian endometrioid carcinoma (1 paper, 2025). "These analyses revealed several novel rearrangements that were predicted to result in in-frame protein fusions in ovarian endometrioid carcinomas, including ATAD1–PTEN, the neurofibromin genes NF1 and NF2, as well as cyclin-dependent and polo-like kinase (PLK) genes CDK7 and PLK5." (PMID 40981433, 2025).
ovarian tumors (1 paper, 2021). "Allele-loss on PLK5-carrying chromosome locus is associated with a 50% increased risk of sporadic ovarian tumors among other neoplasia, suggesting a tumor-suppressive function of PLK5 in the ovary." (PMID 34065956, 2021).
tumor (10 papers, 2012 to 2023). "Subsequently, data from The Human Protein Atlas (derived from TCGA analysis) were further used to verify the prognostic value of tumor PLK5 mRNA expression in NSCLC patients, and high tumor PLK5 mRNA expression was linked to longer OS (P = 0.046)." (PMID 36684318, 2022). "High tumor PLK5 mRNA expression was linked with prolonged DFS in NSCLC patients (P = 0.046)." (PMID 36684318, 2022). "The higher expression of Plk5 in primary tumor could be a response to the DNA damages, but Plk5 silencing by promoter hypermethylation or mutation in the PBD domain to disrupt the expression (as we reported here) allows tumor cells to entering S phase for proliferation disregard their DNA damages." (PMID 26908440, 2016). "Overall, our study demonstrates PLK5 downregulation in multiple cancers, highlighting its role as a tumor suppressor." (PMID 38001717, 2023). "The median (95% CI) DFS of patients with high tumor PLK5 mRNA expression was 43.0 (32.7–53.3) months; the 3-year and 5-year DFS rates were 58.1% and 29.5%, respectively." (PMID 36684318, 2022). "PLK5 protein expression was decreased in tumor tissue {IHC score [mean ± standard deviation (SD)]: 1.6 ± 2.2} compared with nontumor tissue [IHC score (mean ± SD): 3.6 ± 3.1] in NSCLC patients (P < 0.001)." (PMID 36684318, 2022). "In patients with low tumor PLK5 mRNA expression, the median (95% CI) OS was 49.0 (39.1–58.9) months; the 3-year and 5-year OS rates were 74.1% and 35.7%, respectively, in NSCLC patients." (PMID 36684318, 2022). "Tumor-suppressor PLK5 was downregulated in the LumB subtype (log2 FC=-3.29; P=2.58e-69) which is mediated by a CNV-deleted enhancer (chr19:1508023-1536046)." (PMID 36304471, 2022). "Concurrently, high tumor PLK5 protein expression correlated with prolonged OS in NSCLC patients (P = 0.038)." (PMID 36684318, 2022). "Reduced tumor PLK5 mRNA expression was correlated with increased pathological grade (P = 0.034), TNM stage (P = 0.032), and CA125 > 35 U/ml (P = 0.002)." (PMID 36684318, 2022). "The median (95% CI) DFS of patients with low tumor PLK5 mRNA expression was 31.0 (25.7–36.3) months; the 3-year and 5-year DFS rates were 43.0% and 0.0%, respectively, in NSCLC patients." (PMID 36684318, 2022). "In summary, the decrease in PLK5 indicates aggravated tumor burden and an unfavorable prognosis in NSCLC patients." (PMID 36684318, 2022). "Decreased tumor PLK5 protein expression was related to increased pathological grade (P = 0.002), the presence of LYN metastasis (P = 0.001), elevated TNM stage (P = 0.003), and CA125 > 35 U/ml (P = 0.002)." (PMID 36684318, 2022). "Consistent with previous study, cell cycle perturbation profile of Plk5 mRNA suggests that Plk5 is a tumor suppressor at the S phase check-point." (PMID 26908440, 2016). "A possible explanation would be that decreased PLK5 might promote the proliferation and inhibit the apoptosis of tumor cells." (PMID 36684318, 2022). "High tumor PLK5 protein expression was related to prolonged DFS in NSCLC patients (P = 0.007)." (PMID 36684318, 2022). "Correlation of tumor PLK5 protein expression with disease characteristics." (PMID 36684318, 2022). "Correlation of tumor PLK5 mRNA expression with clinical characteristics." (PMID 36684318, 2022). "A PLK5 decrement reflects anabatic tumor burden and poor prognosis in NSCLC patients." (PMID 36684318, 2022). "PLK5 acts as a tumor suppressor in human brain cancer as it is silenced in glioblastoma." (PMID 34065956, 2021). "The protein kinase domain of PLK5 is truncated in humans compared to mice, but the residual protein containing the polo-box binding domain may act as a stress inducible tumor suppressor regulating G1 arrest." (PMID 32575483, 2020). "Interestingly, we also observed PLK5 expression remains consistently low in later stages of cancer, suggesting PLK5 may have a greater role in tumor initiation than cancer progression." (PMID 38001717, 2023). "Indeed, overexpression of PLK5 promotes tumor cell apoptosis." (PMID 35256538, 2022).
tumor (continued). "PLK5 protein and mRNA were detected by immunohistochemistry and RT-qPCR in tumor and nontumor tissues." (PMID 36684318, 2022). "PLK5 mRNA expression was reduced in tumor tissue compared to nontumor tissue in NSCLC patients (P < 0.001)." (PMID 36684318, 2022). "Specifically, the median (IQR) values of PLK5 mRNA expression were 0.324 (0.156–0.490) in tumor tissue and 0.978 (0.449–1.450) in nontumor tissue." (PMID 36684318, 2022). "PLK5 mRNA was reduced in tumor tissue compared with nontumor tissue (P < 0.001); its decline was linked with enhanced pathological grade (P = 0.034), climbed TNM stage (P = 0.032), and abnormal CA125 (P = 0.002)." (PMID 36684318, 2022). "The present study found that PLK5 was decreased in tumor tissues compared to nontumor tissues in NSCLC patients." (PMID 36684318, 2022). "In patients with high tumor PLK5 mRNA expression, the median (95% CI) OS was 62.0 (not available) months; the 3-year and 5-year OS rates were 86.0% and 59.1%, respectively." (PMID 36684318, 2022). "PLK5 protein was decreased in tumor tissue compared to nontumor tissue (P < 0.001)." (PMID 36684318, 2022). "Therefore, decreased PLK5 reflected the enhanced malignant proliferative capacity to some extent; the malignant proliferative ability of tumor tissues was more potent than that of nontumor tissues." (PMID 36684318, 2022). "Conversely to other Plks, Plk5 has no established role in cell cycle regulation and some data indicate that it could act as a tumor suppressor, since its expression diminishes in several cancer cell lines." (PMID 29541386, 2018). "Thus, PLK5 was decreased in tumor tissues compared with nontumor tissues in NSCLC patients." (PMID 36684318, 2022).
cancer (6 papers, 2015 to 2025). A tumor composed of atypical neoplastic, often pleomorphic cells that invade other tissues. "It was reported that loss of heterozygosity and downregulation of PLK5 gene were frequently detected in cancer and its overexpression had an antiproliferative effect in cancer cell lines." (PMID 36304471, 2022). "This revealed consistently downregulated PLK5 expression in these cancers compared to normal tissues." (PMID 38001717, 2023). "We found PLK5 is downregulated in 18 cancer types, including our selected candidates." (PMID 38001717, 2023). "This Plk5 deletion may allow cancer cells to escape from cell cycle arrest in a metastatic site that can potentially induce oxidative stress and DNA damage as shown in a recently reported study." (PMID 26908440, 2016). "In accordance with previous studies, Plk5 is expressed higher in cancer cells of PT." (PMID 26908440, 2016). "Despite being known for its potential among other PLK types (PLK2, PLK3, PLK4, and PLK5), PLK1 is determined recently as a potential oncogenic target across various cancer types due to its extensive research exploration and essential mitotic roles." (PMID 41404416, 2025).
PLK5 also shares sentences with these, for which no sentence is quoted: astrocytoma (1 paper); brain cancer (1); colorectal cancer (1); hyperlipidemia (1); Hypertension (1); lung squamous cell carcinoma (1); Sepsis (1).